BRCA1 (BRCA1 DNA repair associated)
Diseases named in the same sentence as BRCA1 in open-access papers (continued):
Sharing a sentence is not in itself a finding about the gene and the disease.
breast cancer (continued). "Although recent efforts examining polygenic risk of breast cancer have focused on common variants, rare variants that modify risk in BRCA1 and BRCA2 mutation carriers have been identified." (PMID 32866190, 2020). "Pathogenic variants in the two most well‐known high‐risk breast cancer genes, BRCA1 and BRCA2, explain approximately 17% of the familial relative risk." (PMID 32383162, 2020). "During the 1990’s, germline variants in the breast cancer susceptibility genes BRCA1 and BRCA2 were first described as showing increased risk for HBOC." (PMID 32039725, 2020). "Some studies that have evaluated the performance of the breast cancer genetic risk models reported low specificity rates for predicting BRCA1/2-germline mutations." (PMID 32087690, 2020). "For example, upregulated CCNE1, TTK and EXO1 displayed good diagnostic efficacy for screening breast cancer and BRCA1/2-mutant breast cancer." (PMID 31998560, 2020). "Mutations in the BRCA1 gene are associated with a high frequency of associated cancer, and the mean accumulative risk for driving breast cancer was estimated to be more than 50% for BRCA1 carriers by the age of 70 years." (PMID 33324554, 2020). "Targeting the RANK-RANKL axis using the RANKL inhibitor Denosumab offers a potential new avenue as a preventative treatment for breast cancer in women with germline BRCA1 mutations." (PMID 32850393, 2020). "The POSH prospective cohort study analyzed patients with young-onset breast cancer (≤40 years) regarding the BRCA1/2 mutation status." (PMID 32322271, 2020). "In the general population, it is only a small proportion of breast cancer patients who actually exhibit rare mutations in certain genes, such as BRCA1 and BRCA2 genes, that confer the highest risks of developing breast cancer." (PMID 32823908, 2020). "From the point of breast cancer risk and radiation sensitivity, it would be reasonable to screen BRCA1 and BRCA2 mutation carriers according to the same protocol." (PMID 32333294, 2020). "While germline BRCA1/2 mutations occur in 5.3% of unselected breast cancers according to The Cancer Genome Atlas (TCGA), a recent study showed that 11.2% of unselected TNBC cases had deletions in the BRCA1 (8.5%) and BRCA2 (2.7%) respectively." (PMID 33282730, 2020). "A recent prospective study suggests a cumulative risk to the age of 80 years in BRCA1 mutation carriers of up to 72% for breast cancer and up to 44% for ovarian cancer." (PMID 32140806, 2020). "BARD1 is vital in the rapid relocation of BRCA1 to DNA damage sites and has been associated with increased risk of breast cancer in postmenopausal Japanese women." (PMID 32075053, 2020). "For women, increased risk for breast cancer merits similar management to BRCA1 or BRACA2 carriers: clinical breast examination starting at 25 years of age or 5–10 years before the earliest known breast cancer in the family (whichever comes first)." (PMID 33194904, 2020). "BRCA1 deficiency causes oxidative stress and inflammasome activation, which creates a tumor‐associated microenvironment, thereby promoting breast cancer development." (PMID 32195105, 2020). "For instance, a previous study reported a mutation in BRCA1 where a functional single nucleotide variant in the 3′UTR can cause decreased BRCA1 expression, leading to increased breast cancer risk and stage IV breast cancer." (PMID 32858868, 2020). "We conducted a systematic review of evidence related to dietary habits, weight status/change, and physical activity on ovarian and breast cancer risk among women with BRCA1/2 pathogenic variants." (PMID 32165993, 2020). "This study describes the use of WES to screen for pathogenic BRCA1/2 variants alongside clinico-pathological assessments used for interpretation of the findings obtained in Kenyan breast cancer patients." (PMID 32231682, 2020).
breast cancer (continued). "Factors increasing this risk are young age at primary breast cancer, omission of endocrine or chemotherapy in primary breast cancer treatment, and carrying a BRCA-1/2 mutation." (PMID 32770456, 2020). "Breast cancer gene 1 (BRCA1), is the first identified breast cancer susceptibility gene, and is responsible for ~20–25% of hereditary breast cancers and 5–10% of total breast cancers." (PMID 32591500, 2020). "Among other gene mutations, mutations in the BRCA1/2 genes (Breast Cancer 1 and 2; their protein products are commonly called breast cancer type 1 or 2 susceptibility protein) have been reportedly associated with the development of mammary tumors in dogs." (PMID 32005245, 2020). "There are several possible explanations for the higher death rate among the BRCA1 mutation carriers diagnosed with breast cancer in this study compared to ours." (PMID 33238387, 2020). "Both were aligned on supporting its use in women with significant contralateral breast cancer risk i.e., BRCA1/2 mutations, patients with a history of mantle field radiation to the chest before age 30 years." (PMID 31935898, 2020). "Pathogenic variants that occur in the familial breast cancer genes (BRCA1/2) lead to truncated ineffective proteins in the majority of cases." (PMID 32375709, 2020). "In the primary analysis, the hazard ratio (HR) for the association between RRSO and breast cancer risk was 1.23 (95% CI 0.94–1.61) for BRCA1 and 0.88 (95% CI 0.62–1.24) for BRCA2 mutation carriers." (PMID 31948486, 2020). "Researchers have identified that mutations in BRCA1 are associated with a high risk of inherited breast cancer for 40–50% of cases." (PMID 32698331, 2020). "PARP1 inhibitors enhance the effects of DNA damaging drugs in homologous recombination-deficient tumors including tumors with breast cancer susceptibility gene (BRCA1) mutation." (PMID 32405340, 2020). "According to our data, we advanced the frequency of p.Ile1845fs variant and we confirmed that BRCA1: p.Ile1845fs variant was associated with increased risk of breast cancer (OR = 2.36, 95%CI = 1.26–4.89, P = 0.004)." (PMID 31908633, 2020). "A recent large prospective study showed a lifetime-risk for breast cancer development by the age 80, to be 72% for carriers of a pathogenic variant in BRCA1 and 69% for BRCA2, respectively." (PMID 32727387, 2020). "The 10-year occurrence rates of breast cancer among patients with prior ovarian cancer were 12% in BRCA1 mutation carriers and 2% in BRCA2 mutation carriers." (PMID 32250967, 2020). "The result of the EMBRCA phase III study (NCT01945775) also confirms that single-agent talazoparib provides a significant benefit over standard chemotherapy with respect to PFS among patients with advanced breast cancer and a germline BRCA1/2 mutation." (PMID 32122376, 2020). "Mammary tumor development in dogs and women has been associated with deregulation of BRCA1/2 gene function." (PMID 32411603, 2020). "BRCA1 mutations account for almost one-quarter of cases of hereditary familial breast cancer in humans, and the estimated lifetime risk of developing breast cancer for women with BRCA1 germline mutations is 40–80%8." (PMID 32978388, 2020). "Women with an inherited BRCA1 mutation have a lifetime risk of 70–80% of developing breast cancer and 37–62% of developing ovarian cancer." (PMID 33013205, 2020). "Men carrying mutations in BRCA1/2 have been reported to develop melanomas or pancreatic, prostatic, and breast cancers." (PMID 33054725, 2020). "BRCA1 deficiency impairs mitophagy, which suggests that more damaged mitochondria accumulate in BRCA1 mutant breast cancer cells under mitochondrial stress." (PMID 32195105, 2020). "The confirmed results from Phase II clinical trials reveal that antibodies against PD-L1 (durvalumab or pembrolizumab) in combination with PARPis (olaparib or niraparib) exhibit a good response against germline BRCA1/2-mutated breast cancer and other cancers." (PMID 33324554, 2020).
breast cancer (continued). "Up to 10% of breast cancer cases can be attributed to hereditary factors comprising personal or family history of breast or ovarian cancer and inherited gene mutations such as BRCA1 and BRCA2 among others." (PMID 32711446, 2020). "BRCA1 mutated breast cancer PDX models resistant to PARP inhibitors showed reduced PARP1 expression levels." (PMID 32029455, 2020). "Similar results were shown in another study demonstrating a 10-year cumulative contralateral breast cancer risk of 23.9% (BRCA1: 25.5%; BRCA2: 17.2%) in patients <41 years, compared to 12.6% in the 41–49 year group (BRCA1 15.6%; BRCA2 7.2%)." (PMID 31935898, 2020). "Studies assessing the application of polygenic factors for familial cancer have reported that PRS was predictive of breast cancer risk among women from high-risk families with uninformative BRCA1/2 result." (PMID 32066492, 2020). "In women who carry BRCA1/2 gene mutations, high energy intake is associated with increased breast cancer risk compared to women with low energy intake." (PMID 33212987, 2020). "In our study, one patient with BRCA1 gene mutation has shown the early-onset of breast cancer who’s age at diagnosis was 35 years." (PMID 32856854, 2020). "In conclusion, the efficacy of risk-based breast cancer screening practices, such as MRI, for BRCA1 and BRCA2 mutation carriers shows promise in terms of increased cancer detection rates and decreased mortality." (PMID 31734900, 2020). "In the overall analysis, BRCA1: p.Ile1845fs variant showed a higher frequency in breast cancer cases (0.40%) than in controls (0.17%) with a greater than two-fold increased breast cancer risk (OR = 2.44, 95% CI = 1.12–5.34, P = 0.034)." (PMID 31908633, 2020). "Early studies estimated that RRSO provided approximately a 50% reduction in the risk of breast cancer in women with BRCA1 and BRCA2 mutations, particularly if performed before age 45 years." (PMID 32337493, 2020). "Olaparib (AZD-2281, MK-7339, Lynparza) was the first PARP inhibitor that entered clinical trials and was investigated as a targeted therapeutic agent for breast cancer involving BRCA1/2 mutation." (PMID 33324554, 2020). "The PRSER- was associated with breast cancer risk for BRCA1 carriers (per SD HR = 1.28, 95% CI = 1.14–1.44, P = 4.4×10−5)." (PMID 32665703, 2020). "For breast cancer, they include such factors as BRCA1/2 mutations, family history of breast cancer, reproductive history, breast density, hormone replacement therapy, physical inactivity, overweight/obesity, and alcohol use." (PMID 33302472, 2020). "Another study detected germline or somatic BRCA1 or BRCA2 inactivating mutations or BRCA1 promoter methylation in 90 out of 560 breast cancer samples." (PMID 33158305, 2020). "The discovery of the second breast cancer predisposing gene was followed by the BRCA1 cloning, and subsequently, the race to clone BRCA2 was completed the following year by the same research team." (PMID 32269964, 2020). "Taken together, mutations in BRCA1/2 account for 25–40% of FBCs, and up to 10% of all breast cancers." (PMID 32300589, 2020). "Breast cancer patients historically benefitted from population-based genetic research performed in South Africa, which led to the development of founder-based BRCA1/2 diagnostic tests." (PMID 33643918, 2020). "In breast cancer patients, the tumor phenotype differs according to the BRCA1 or BRCA2 germline mutation status." (PMID 32341426, 2020). "All of the women had a history of breast cancer, with a large portion of them being BRCA1 or BRCA2 mutation carriers." (PMID 32722165, 2020). "PARP1 and PARP2 play critical roles in regulating DNA repair and PARP inhibitors have been approved for the treatment of BRCA1/2-mutated ovarian and breast cancers." (PMID 32029902, 2020).
breast cancer (continued). "Breast cancer in young people is more often associated with germline mutations in the BRCA1/2 genes which constitute an increased familial risk for breast and ovarian cancer." (PMID 31940967, 2020). "BRCA1 5382insC, is the second most recurrent mutation reported in the BRCA1 gene in different countries, according to the breast cancer information core (BIC)." (PMID 32102521, 2020). "Genome-wide association studies by the Breast Cancer Association Consortium (BCAC) and Consortium of Investigators of Modifiers of BRCA1/2 (CIMBA) have previously found genetic variants at 8p12 associated with breast cancer risk." (PMID 31936698, 2020). "Women who carry mutations in BRCA1 or BRCA2 face 60% to 80% elevated lifetime risk to develop breast cancer by the age of 80." (PMID 32053991, 2020). "One study evaluated risk-reducing interventions in 40-year-old women with BRCA-1 mutations at high risk for uterine cancers additionally considering the risk for developing breast cancer and ovarian cancer." (PMID 32664613, 2020). "In bilateral ER-negative patients with a family history of breast cancer, the BRCA1 mutation rate was nearly 60%." (PMID 32117708, 2020). "In North Africa, several BRCA1/2 founder mutations were identified among which BRCA1-c.798_799delTT that was reported in 9.8% and 36.4% of familial and sporadic Algerian breast cancer cases, respectively." (PMID 33240314, 2020). "Nevertheless, mono-allelic germline BRCA1/2 mutations show a significant enrichment in breast cancer patients, compared with the general population." (PMID 33067557, 2020). "Nearly 5% of breast cancers occur in a context of genetic predisposition, mostly represented by monoallelic pathogenic variants of BRCA1, BRCA2 or PALB2 genes." (PMID 33302444, 2020). "In vitro evidence also supports a role for BCAAs in breast cancer development in human breast epithelial cells, with research demonstrating that a knock-in of a single allele BRCA1 mutation led to increased BCAAs12." (PMID 33024201, 2020). "High-penetrance breast cancer susceptibility genes, such as BRCA1 and BRCA2, explain only a small fraction of breast cancers in the general population because of their low carrier rates." (PMID 33226082, 2020). "The breast cancer susceptibility gene 1 (BRCA1) is a major breast cancer suppressor gene, which encodes a protein critical for maintaining DNA integrity and genomic stability." (PMID 32195105, 2020). "The occurrence rate of BRCA1 mutations is found to be high in South Asian countries where early onset of breast cancer is common." (PMID 32856854, 2020). "The protective effect of breast-feeding against breast cancer has been shown by studies for BRCA1 mutation carriers." (PMID 32070378, 2020). "A strong association between ER-negative variants and breast cancer risk in BRCA1 mutation carriers was also reported." (PMID 32066492, 2020). "BRCA1/2 have been primarily investigated for diagnostic purposes because their mutations show high penetrance, conferring the 5-fold higher risk of breast cancer in P/LP variant carriers compared to the general population." (PMID 32957588, 2020). "The increased allelic imbalance in the BRCA1 gene is associated with increased breast cancer risk and SNPs (single nucleotide polymorphsims) on the mutated allele of KCNQ1, causing allelic imbalance leading to a less severe form of LQT1." (PMID 32392813, 2020). "It was also found that TMB with mutations of BRCA1 or BRCA2 was a prognosis signature in breast cancer, which was able to predict the treatment response." (PMID 32729618, 2020). "The NCCN guidelines recommend genetic testing for BRCA1/2 mutations based on age at breast cancer diagnosis and burden of breast, ovarian, and other related cancers in the family." (PMID 32881420, 2020).
breast cancer (continued). "It was reported that the risk of breast cancer increased substantially between the ages of 30 and 50 years for BRCA1 carriers, while the risk was highest between the ages of 40 and 60 years for BRCA2 carriers, which was simulated to our results." (PMID 31912664, 2020). "This study investigates the prevalence of multifocality/multicentricity in a cohort of BRCA1/2 mutation carriers with breast cancer from Northern Ireland via cross‐sectional analysis." (PMID 32022473, 2020). "Germline mutations in the BRCA1 gene occurring in breast cancer cases often result in a complete loss of function of BRCA1." (PMID 32456160, 2020). "About 50% of hereditary breast cancers and 70~80% of hereditary ovarian cancer patients have BRCA1 mutations in their germ cells, while sporadic ovarian cancers have a BRCA1 mutation rate of less than 5%." (PMID 32356124, 2020). "Genomewide association studies have identified a number of loci that alter the breast cancer risk in BRCA1/2 mutation carriers." (PMID 32255263, 2020). "Yet, neoadjuvant talazoparib, administered as a single-agent in patients with HER2-negative breast cancer and germline BRCA1/2 mutation, achieved an impressive pathological complete response rate of nearly 50%." (PMID 32471249, 2020). "Intuitively, it would seem that women with a BRCA1 mutation would most likely be the ones to consider BPM as they have a higher breast cancer risk than BRCA2 mutations." (PMID 31832891, 2020). "As a cancer treatment drug, olaparib is first defined as the HR deficient tumor treatment, and it is fully approved by FDA for serous ovarian cancer and breast cancer treatment with germline BRCA1 or BRCA2 mutations." (PMID 32046300, 2020). "Somatic BRCA mutations which are present only in the tumor cells, have been reported to be up to 15–30% of all BRCA1/2 mutations, and can be found in various malignancies, such as 3% of breast cancer cases, and over 12% of advanced prostate cancer patients." (PMID 32493233, 2020). "In the present study, the upregulated expression and corresponding diagnostic value of TTK in BRCA1/2-mutant breast cancer suggested that the role of TTK in this type of breast cancer is equally noteworthy." (PMID 31998560, 2020). "In the total sample, only few breast cancer-free women (462; 1.3%) were tested for BRCA1 and/or BRCA2 germline pathogenic variants, including both complete and targeted testing." (PMID 32565540, 2020). "The loss of heterozygosity of BRCA1 in somatic breast cancer has been shown to share genotype/phenotype features with familial breast cancer and have a defect of the DNA repair pathway." (PMID 32235451, 2020). "In contrast, Nkondjock and colleagues case-control study observed an association between ≥6 cups caffeinated coffee/day among 652women with BRCA1 pathogenic germline gene variant and breast cancer risk (OR 0.25, 95%CI 0.09,0.71)." (PMID 32165993, 2020). "Patients with overall BRCA1/2 mutations tended to show a higher rate of BRCA1/2-related family history and breast cancer history compared to patients with wild-type BRCA1/2." (PMID 32164585, 2020). "The EMBRACA trial studied the efficacy of talazoparib, another PARP inhibitor, on advanced breast cancer patients with germline BRCA1/2 mutations and who had been previously treated with chemotherapy." (PMID 32846967, 2020). "In the case of DHC, its synthetic lethality toward BRCA1-deficient breast cancer lines also indicates its potential in combinatorial cancer therapy." (PMID 33143019, 2020). "It’s reported that FANCD2 was highly expressed in BRCA1/2-mutated breast cancer, ovarian cancers and uterine cancers." (PMID 32563252, 2020).